MUC5AC (mucin 5AC, oligomeric mucus/gel-forming)
Diseases named in the same sentence as MUC5AC in open-access papers (continued):
Sharing a sentence is not in itself a finding about the gene and the disease.
bronchiolitis (2 papers, 2019 to 2025). Inflammation of the bronchioles characterized by swelling of the bronchioles and mucus accumulation. "Also, reduced IFN-γ levels were detected in children with moderate bronchiolitis; however, in children with severe bronchiolitis, the levels of IL-17A and MUC5AC were increased." (PMID 30936869, 2019).
cervical carcinoma (2 papers, 2019 to 2025). A carcinoma arising from either the exocervical squamous epithelium or the endocervical glandular epithelium. "In cervical carcinoma, the most immunogenic epitopes were found in proteins expressed by HSPG2 and MUC5AC." (PMID 41471728, 2025).
chronic cholecystitis (2 papers, 2023 to 2025). "At first glance, MUC5AC upregulation seems to be more consistent in studies on chronic cholecystitis (93–94.3% positivity in three studies using various antibodies) than studies on hepatolithiasis (17%, 40%, and 89% in three studies, respectively, using immature antibodies)." (PMID 36672382, 2023). "Several studies on gallbladder tissues (with immature CLH2 or unknown-maturity polyclonal Dako antibodies) found significantly lower MUC5AC expression in invasive GBC than gallbladder polyps, adenomas, or chronic cholecystitis." (PMID 36672382, 2023).
ciliary dyskinesia (2 papers, 2016 to 2025). "Altered mucus composition (MUC5AC overexpression) and ciliary dyskinesia further impair mucus clearance, perpetuating a vicious cycle of mucus retention." (PMID 40672703, 2025). "Chronic infections or irritants will upregulate IL-13 and IL-17 in nasal epithelium, promoting goblet cell hyperplasia, overexpression of MUC5AC and MUC5B mucins, and ciliary dyskinesia, ultimately driving CRSwNP." (PMID 40672703, 2025).
clear cell renal cell carcinoma (2 papers, 2017 to 2021). "However, the clinic pathologic features and prognostic values of MUC5AC in clear-cell renal cell carcinoma (ccRCC) have not been reported up to now." (PMID 28938681, 2017).
corneal ulcer (2 papers, 2009 to 2023). Area of epithelial tissue loss from corneal surface; associated with inflammatory cells in the cornea and anterior chamber. "In a previous study, we reported that there is a compensatory increase in MUC5AC expression just before and at the time of corneal ulceration in atopic keratoconjunctivitis (severe ocular surface disease), and the expression declines with the chronicity of inflammation." (PMID 36675473, 2023). "The goblet cell densities and mRNA expressions of MUC5AC showed a dramatic reduction in atopic patients with a severe epithelial disease, especially in patients with corneal ulcers, relative to patients without any epithelial disease and healthy control subjects." (PMID 19158956, 2009).
fungal infection (2 papers, 2015 to 2023). "PM-242H-treated, salmeterol-exposed mice further showed marked reductions in Muc5ac mRNA expression while still controlling the airway fungal infection." (PMID 26605551, 2015).
gallbladder adenocarcinoma (2 papers, 2021 to 2024). A carcinoma that arises from glandular epithelial cells of the gall bladder. "Specifically, MUC1 expression exhibits a significant elevation in gallbladder adenocarcinoma compared to chronic cholecystitis, while MUC5AC expression tends to diminish in neoplastic conditions relative to chronic inflammation." (PMID 38786750, 2024). "Implications regarding mucin types, particularly MUC1 and MUC5AC, have emerged in the context of malignant tumor development, impacting the biological characteristics and advancement of gallbladder adenocarcinoma." (PMID 38786750, 2024).
gallstones (2 papers, 2023 to 2025). Solid crystalline precipitates in the biliary tract, usually formed in the gallbladder, resulting in the condition of cholelithiasis. "A significant level of MUC5AC expression was associated with inflammation and pigmented brown gallstones." (PMID 36600870, 2023). "Additionally, previous studies and our results indicate that epithelial MUC1 seems to play a key role in the up‐regulation of the gel‐forming MUC5ac during cholesterol gallstone formation." (PMID 39932450, 2025).
gastric adenoma (2 papers, 2013 to 2025). A neoplastic polyp that arises from the stomach. "Histological examination revealed a low-grade foveolar-type gastric adenoma (FGA), predominantly expressing MUC5AC by immunohistochemistry." (PMID 39939466, 2025). "For gastric adenoma and tub1/tub2-type GC, more undifferentiated tumors tend to show higher expression of CTSE with MUC5AC and lower expression of MUC2 in tumors, but they tend to present lower expression of CTSE, MUC5AC and MUC2 in background mucosa." (PMID 23451082, 2013).
glaucoma (2 papers, 2010 to 2023). Increased pressure in the eyeball due to obstruction of the outflow of aqueous humor. "Both phacotrabeculectomy and short-term anti-glaucoma medications can decrease the MUC5AC in the tear fluid of primary angle-closure glaucoma patients." (PMID 21139981, 2010). "One of the reasons for the reduction of MUC5AC is the preservatives used in the anti-glaucoma medications." (PMID 21139981, 2010). "In the present study, we evaluated the quantity of MUC5AC in the tear fluid of patients with glaucoma combined with cataract after the use of topical anti-glaucoma medications for less than 6 months, and monitored the MUC5AC change of the patients after phacotrabeculectomy." (PMID 21139981, 2010). "For MUC5AC, which is secreted solely by conjunctival goblet cells, this indicates that, even for a relatively short-term topical anti-glaucoma medication therapy, the goblet cells of the patients may be decreased considerably, numerically and/or functionally." (PMID 21139981, 2010).
infertile (2 papers, 2022 to 2025). "Complementary studies analysed the intra-organoid-fluid (IOF) from fertility, and infertile patient organoids further revealed that MUC5AC was significantly increased in infertile IOF compared to fertile IOF, a finding corroborated via proteomic analysis." (PMID 40628401, 2025). "We demonstrated that MUC5AC was abnormally elevated in IOF in organoids from infertile women and confirmed the finding by immunoblotting." (PMID 36589798, 2022). "Similar to the proteomics data, MUC5AC was significantly increased in infertile IOF compared to fertile IOF (P<0.05)." (PMID 36589798, 2022). "We confirmed the differential secretion of MUC5AC between fertile and infertile groups by immunoblotting." (PMID 36589798, 2022).
injury (2 papers, 2023 to 2024). Damage inflicted on the body as the direct or indirect result of an external force, with or without disruption of structural continuity. "Herein, we investigated the formation of bacterial biofilms and MUC5AC and MUC5B gene expression levels in samples from 80 patients admitted for either acute nasal trauma (14 patients, control group) or chronic nasal pathology (66 patients, CRS group)." (PMID 36902594, 2023).
intrahepatic cholangiocarcinoma (2 papers, 2013 to 2024). A carcinoma that arises from the intrahepatic bile duct epithelium in any site of the intrahepatic biliary tree. "The conventional intrahepatic cholangiocarcinoma (ICC) frequently expressed MUC5AC, but no MUC2, in carcinoma cells." (PMID 23347460, 2013).
lung mucinous adenocarcinoma (2 papers, 2022 to 2023). "In addition to enabling the development of mucinous lung adenocarcinoma, LKB1 loss is associated with increased expression of markers of gastric differentiation, such as TFF1 and MUC5AC in human and mouse lung cancer." (PMID 35228570, 2022). "Moreover, HNF-4α is reported as part of the signature genes of invasive lung mucinous adenocarcinoma, together with FOXA3, SPDEF and mucins, such as MUC5AC, MUC5B, and MUC3." (PMID 36674438, 2023).
Lynch syndrome (2 papers, 2017 to 2023). An autosomal dominant hereditary neoplastic syndrome characterized by the development of colorectal carcinoma and a high risk of developing endometrial carcinoma, gastric carcinoma, ovarian carcinoma, renal pelvis carcinoma, and small intestinal carcinoma. "However, when evaluating 175 microsatellite-unstable (MSI-H) CRCs, of which 76 were sporadic and 99 were associated with lynch syndrome, MUC5AC-positive tumors were significantly associated with sporadic tumors (54% vs. 27% for lynch syndrome; p-value < 0.001)." (PMID 36900282, 2023). "Tumors linked to Lynch syndrome and FCCTX showed significant differences, primarily related to frequent expression of CK20 and nuclear β-catenin in FCCTX and relative over-expression of MUC2, MUC5AC and MUC6 in Lynch syndrome." (PMID 28824332, 2017). "Our study on the secreted gel-forming mucins (MUC2, MUC5AC, and MUC6) demonstrated significantly higher values in the Lynch syndrome than in the FCCTX tumors." (PMID 28824332, 2017). "Differences were identified for CK20 and nuclear β-catenin, which were significantly more often expressed in FCCTX than in Lynch syndrome (p < 0.001), whereas MUC2, MUC5AC and MUC6 were overexpressed in Lynch syndrome tumors compared with FCCTX tumors (p = 0.001, < 0.01, and < 0.001, respectively)." (PMID 28824332, 2017). "We further found that FCCTX tumors generally mimicked the profile of the non-neoplastic colorectal mucosa, with CK20+, MUC5AC- and MUC6-, which contrasted to the expression pattern in the Lynch syndrome tumors." (PMID 28824332, 2017).
melanoma (2 papers, 2013 to 2020). A malignant, usually aggressive tumor composed of atypical, neoplastic melanocytes. "A specific protein profile was discovered for each cell line, e.g., EGFR in OSCC, Muc5AC in PDAC, and FN1 in melanoma vesicles." (PMID 32886718, 2020).
mucinous colorectal adenocarcinoma (2 papers, 2019 to 2022). "Based on its molecular context, mucinous colorectal adenocarcinoma is associated with the overexpression of mucin 2 (MUC2) and mucin 5AC (MUC5AC) proteins." (PMID 30922401, 2019). "However, concerning the differences between the gene expression levels in mucinous and non-mucinous colorectal adenocarcinomas, recent literatures suggest that MUC2 and MUC5AC could serve as potential targets for future treatments for mucinous colorectal adenocarcinoma." (PMID 30922401, 2019).
mucinous ovarian cancer (2 papers, 2015 to 2023). An invasive malignant neoplasm that arises from the ovary and is characterized by the presence of malignant epithelial cells that contain intracytoplasmic mucin and may resemble the epithelial cells of the endocervix or gastrointestinal tract. "The detailed study of MUC5AC O-glycosylation changes during mucinous ovarian cancer progression could lead to the development of assays recognizing both the apoprotein component and specific glycans of MUC5AC." (PMID 26075384, 2015).
Mycoplasma pneumoniae pneumonia (2 papers, 2024 to 2025). Interstitial pneumonia caused by extensive infection of the lungs (lung) and bronchi, particularly the lower lobes of the lungs, by mycoplasma pneumoniae in humans. "It is recognized in the literature that Mycoplasma pneumoniae pneumonia coincident with plastic bronchitis correlates with modulated expression of inflammatory proteins such as MUC5AC, MUC5B, and layilin." (PMID 38930514, 2024).
rectal cancer (2 papers, 2019 to 2021). A primary or metastatic malignant neoplasm that affects the rectum. "MUC5AC expression strongly depended on the tumor location and gradually decreased from proximal (27.4% of cecum cancers) to distal (10.6% of rectal cancers; p < 0.0001)." (PMID 33373033, 2021).
rhinitis (2 papers, 2021 to 2022). An inflammation of the mucous membrane lining the nose, usually associated with nasal discharge. "Therefore, we used HNEpCs to investigate the mechanisms underlying the anti-rhinitis activity of CSLW and found that CSLW significantly inhibited the accumulation of eosinophils and upregulation of periostin, MUC5AC, and ROS in IL-4- and IL-13-stimulated HNEpCs in a concentration-dependent manner." (PMID 36421442, 2022). "We also studied altered MUC5AC and MUC5B gene expression consistently observed in rhinitis models, therefore, mucins expression in sinus mucosa was analyzed using RT-qPCR analysis, in particular MUC5AB and MUC5AC expression." (PMID 34638811, 2021).
Rhinosinusitis (2 papers, 2014 to 2024). "Our systematic review and meta‐analysis aimed to comprehensively investigate the association between MUC5AC expression and rhinosinusitis." (PMID 39482799, 2024). "Our meta‐analysis robustly demonstrates a significant association between elevated MUC5AC expression and rhinosinusitis risk." (PMID 39482799, 2024). "Muc5AC expression and rhinosinusitis association was analyzed by STATA 14.0." (PMID 39482799, 2024). "The underlying mechanisms driving MUC5AC dysregulation in rhinosinusitis warrant exploration." (PMID 39482799, 2024). "Exploring the functional implications of increased MUC5AC expression in rhinosinusitis is crucial for understanding its role in disease pathogenesis." (PMID 39482799, 2024). "While individual studies have reported increased MUC5AC levels in rhinosinusitis patients, our meta‐analysis provides a comprehensive synthesis of existing evidence, offering a more nuanced and statistically robust understanding of this association." (PMID 39482799, 2024). "The synthesis of data from 16 studies, encompassing 1448 patients with rhinosinusitis, consistently revealed a significant up‐regulation of MUC5AC in both CRSwNP and CRSsNP patients compared with controls." (PMID 39482799, 2024). "In conclusion, our systematic review and meta‐analysis provide compelling evidence for the up‐regulation of MUC5AC expression in patients with rhinosinusitis." (PMID 39482799, 2024). "Elevated MUC5AC expression likely reflects an adaptive response to the inflammatory environment, emphasizing its potential as a molecular marker in rhinosinusitis pathogenesis." (PMID 39482799, 2024). "The inflammatory milieu characteristic of rhinosinusitis, marked by immune cell infiltration, cytokine release, and tissue remodeling, likely contributes to the observed up‐regulation of MUC5AC." (PMID 39482799, 2024). "This association holds true for both protein‐level and IHC positive area assessments, reinforcing the robustness and consistency of MUC5AC up‐regulation at the molecular level in the context of rhinosinusitis." (PMID 39482799, 2024). "Therapeutically, targeting MUC5AC dysregulation could offer a novel approach to rhinosinusitis management." (PMID 39482799, 2024). "Our findings align with and extend the existing literature on MUC5AC expression in rhinosinusitis." (PMID 39482799, 2024).
silicosis (2 papers, 2021 to 2022). Silicosis is a respiratory disease caused by breathing in (inhaling) silica dust. "Combined with our current data, improving mucociliary function via increasing the expression of MUC5AC may be an effective way to ameliorate silicosis progression." (PMID 34149803, 2021). "Further, the protein levels of MUC5AC and FGF10 detected by immunohistochemistry were significantly decreased in silicosis lungs, especially in epithelium." (PMID 34149803, 2021). "This analysis revealed both common and specific regulations in silicosis, along with several critical genes (e.g., MUC5AC and FGF10), which are potential drug targets for silicosis treatment." (PMID 34149803, 2021). "For example, Plerixafor inhibits the CXCR4 chemokine receptor, which is induced in silicosis; Retinoic acid may both inhibit the expression of COL2A1 and activate MUC5AC." (PMID 34149803, 2021).
urachal adenocarcinomas (2 papers, 2018 to 2022). "A comparable distribution was detected for MUC2 and MUC5AC with high positivity rates in urachal adenocarcinomas (100% and 92%) and lower rates in colorectal and primary bladder adenocarcinomas." (PMID 36010242, 2022). "A comparable distribution was detected for MUC2 and MUC5AC with high positivity rates in urachal adenocarcinomas (100% and 92%) and lower rates in colorectal and primary bladder adenocarcinomas, however, with significant overlap." (PMID 29721106, 2018). "Useful biomarkers of urachal adenocarcinomas, like alpha-methylacyl-CoA racemase (AMACR, p504s), CD15 (Leu-M1), carcinoembryonic antigen (CEA), CK34βE12 (high-molecular weight cytokeratin), GATA binding protein 3 (GATA3), mucin 2 (MUC2), and mucin 5AC (MUC5AC), should be taken into consideration." (PMID 36010242, 2022).
adenocarcinoma in situ (1 paper, 2017). A lesion in which the normally situated glands are partially or completely replaced by atypical cells with malignant characteristics. "Immunostaining for MUC5AC and MUC6 confirmed the diagnosis of adenocarcinoma in situ arising from Brunner's gland hyperplasia." (PMID 28512587, 2017).
ampullary adenocarcinoma (1 paper, 2011). "For example, normal pancreatic tissue mainly expresses MUC1 and MUC6, while ampullary adenocarcinoma mainly expresses MUC1 and MUC5AC, along with MUC6 and MUC2." (PMID 22027009, 2011). "Expression of MUC1 was high (72%) in ampullary adenocarcinoma, while expressions of MUC2, MUC5AC, and MUC6 were lower." (PMID 22027009, 2011). "This study explored the relationships between diagnosis, identification, and survival of ampullary adenocarcinoma and the expressions of MUC1, MUC2, MUC5AC, and MUC6." (PMID 22027009, 2011).
Anal fistula (1 paper, 2014). An abnormal connection between the epithelialised surface of the anal canal and the perianal skin. "In the 3 CD cases having ectopic MUC5AC expression, increases in CRP and CDAI (CDAI ≥150) were observed as signs of flare-up in 2 patients, while the remaining patient developed anal fistula, for which the Seton technique was performed surgically." (PMID 24829572, 2014).
angiosarcoma (1 paper, 2021). A malignant tumor arising from the endothelial cells of the blood vessels. "MUC5AC expression was also seen in 1 case each of angiosarcoma and medullary thyroid carcinoma." (PMID 34547930, 2021).
Autoimmunity (1 paper, 2019). The occurrence of an immune reaction against the organism's own cells or tissues. "In addition to the protective role of stimulating the production of many antibacterial proteins (b-defensins, mucins: MUC5AC, MUC5B, S100 calgranulins, lipocalin 2), IL-17 appears to be important in autoimmunity as evidenced by the experimental autoimmune encephalomyelitis (EAE)." (PMID 31468124, 2019).
bacterial vaginosis (1 paper, 2016). Infection caused by bacterial overgrowth in the vagina. "In this study we report the changes in membrane bound (MUC1 and MUC4) and gel-forming mucins (MUC5AC and MUC7) relative to the influence of hormones and the presence of the abnormal vaginal flora of bacterial vaginosis." (PMID 27437931, 2016).
benign cystadenoma (1 paper, 2015). "In the present study, MUC5AC was the only mucin-type glycoprotein that was identified by proteomic analyses of acidic high-molecular weight proteins obtained from three mucinous ovarian cyst fluids (benign cystadenoma, low-grade stage I and low-grade stage III adenocarcinomas)." (PMID 26075384, 2015).
biliary tract diseases (1 paper, 2022). "A study reported that bile MUC5AC couldn’t distinguish benign from malignant biliary tract diseases." (PMID 36389727, 2022). "However, whether bile MUC5AC expression could distinguish benign and malignant biliary tract diseases is still controversial." (PMID 36389727, 2022).
breast ductal adenocarcinoma (1 paper, 2014). A breast carcinoma arising from the ducts. "In breast ductal adenocarcinomas, MUC2 and MUC5AC are localized in cytoplasm with granular staining pattern, whereas distribution of MUC5B expression changes from apical localization in non-malignant breast cells to cytoplasmic and non-apical localization in malignant ductal breast carcinoma." (PMID 25261375, 2014).
cholangitis (1 paper, 2019). An acute or chronic inflammatory process affecting the biliary tract. "Additionally, evaluation of serum to bile ratio of MUC5AC (better than serum level alone) showed excellent diagnostic performance for differentiating CC from cholangitis and cholelithiasis." (PMID 30875782, 2019).